ABL2 (ABL proto-oncogene 2, non-receptor tyrosine kinase)
Diseases named in the same sentence as ABL2 in open-access papers (continued):
Sharing a sentence is not in itself a finding about the gene and the disease.
infection (3 papers, 2016 to 2023). The state of being infected such as from the introduction of a foreign agent such as serum, vaccine, antigenic substance or organism. "We conducted infection experiments using the mutated S2 strain to assess the Abl2-mediated actin backbone regulatory pathway in CEKs, using qRT-PCR to measure the relative expression of host factors." (PMID 37376546, 2023). "Abl2 can mediate the complex interaction of the virus–host cytoskeleton during viral particle entry and escape, as well as the ensuing infections." (PMID 37376546, 2023). "The infection only resulted in a minor increase in Abl2 expression, as indicated through rSczy3S2-G543S-Q544S-S553T-F557Y." (PMID 37376546, 2023). "Here, we used protocols to selectively quantify infection via virus-membrane and membrane-membrane fusion and found that the imatinib effect on these processes are both Abl1 and Abl2 refractory." (PMID 35388061, 2022). "Abl2 expression was consistently increased at 24 and 48 hpi following rSczy3 infection." (PMID 37376546, 2023). "Furthermore, the Abl2 gene expression was notably enhanced after S2 protein expression and subsequent rSczy3 infection (p < 0.001)." (PMID 37376546, 2023). "To find out whether the expression of the viral S2 protein activates CTSB and Abl2, we used qRT-PCR to analyze the relative expression in the rSczy3 infection, the S2 transfected group, and the mock groups." (PMID 37376546, 2023). "We used the rescued strain rSczy3 to infect CEKs and performed qRT-PCR to evaluate the relative expression levels of CTSL, CTSB, Abl1, Abl2, IFITM3, ADAM17, TMPRSS2, NRP1, and CD74 at 12 and 24 h post-infection." (PMID 37376546, 2023). "Infection of both SARS-CoV-2 and a surrogate lenti-Spike were blocked by imatinib, a widely used inhibitor of the non-receptor Abl1 and Abl2 tyrosine kinases." (PMID 35388061, 2022).
cardiovascular diseases (1 paper, 2015). "Another biological function describrd cardiovascular disease gene as ABL2, ABL2 and EDNRB." (PMID 26345457, 2015).
hematologic malignancies (1 paper, 2013). "TEL fusion proteins with other tyrosine kinases, such as ABL1, ABL2, JAK2, NTRK3, FFGR3, and PDGFRB, have also been associated with various hematologic malignancies, though direct comparisons between these fusion proteins in mouse models is not complete." (PMID 24116232, 2013).
ABL2 also shares sentences with these, for which no sentence is quoted: acute myeloid leukemia (2 papers); breast tumor (2); allergic asthma (1); Alzheimer disease (1); Cognitive impairment (1); colon cancer (1); colorectal cancer (1); diabetic nephropathy (1); endometrial cancer (1); epilepsy (1); esophageal squamous cell carcinoma (1); Ewing sarcoma (1); follicular lymphoma (1); ganglioglioma (1); hematologic neoplasms (1); kidney carcinomas (1); leiomyosarcoma (1); lung injury (1); metastatic melanoma (1); mucoid adenocarcinoma (1); mucosal (1); myxoma (1); neurodegenerative disease (1); osteosarcoma (1); renal cell carcinoma (1); skin cancer (1); small cell lung carcinoma (1); thymoma (1); undifferentiated pleomorphic sarcoma (1).